MIR5186 (microRNA 5186)
Synonyms: hsa-mir-5186
Gene: MicroRNA gene on chromosome 3 (151,565,876 to 151,565,995, reverse strand). Ensembl gene ENSG00000264330.
Homologues: Orthologues: chimpanzee MIR5186 (100% identical).